FAM193A (family with sequence similarity 193 member A)
Synonyms: C4orf8; RES4-22
Tractability: Antibody: the Human Protein Atlas places it where antibodies can reach. PROTAC: ubiquitination databases record sites on it; its protein half-life has been measured.
Gene: Protein-coding gene on chromosome 4 (2,536,646 to 2,732,573, forward strand). Ensembl gene ENSG00000125386.
Subcellular location: Nucleus; Cytoplasm
Subcellular location (Human Protein Atlas): Cytosol; Plasma membrane
Gene Ontology:
Molecular function: protein binding
Cellular component: cytoplasm; nucleus
Genetic constraint (gnomAD): Loss-of-function variants: 20 observed, 107.2 expected, observed/expected ratio (o/e) 0.19, 90% interval 0.13 to 0.27. The upper end of that interval is the gene's LOEUF score, 0.27, which puts it in group 1 of 6, group 1 being the genes least tolerant of losing a copy. Missense variants: 1,439 observed, 1,562.7 expected, observed/expected ratio (o/e) 0.92, 90% interval 0.88 to 0.96. Synonymous variants: 657 observed, 613.5 expected, observed/expected ratio (o/e) 1.07, 90% interval 1 to 1.14.
Homologues: Orthologues: macaque FAM193A (99% identical), chimpanzee FAM193A (95% identical), mouse Fam193a (88% identical), rat Fam193a (86% identical), rabbit FAM193A (85% identical), guinea pig FAM193A (84% identical), pig FAM193A (81% identical), dog FAM193A (72% identical), tropical clawed frog fam193a (70% identical), zebrafish fam193a (55% identical), Drosophila melanogaster CG7518 (18% identical). Paralogues in human: FAM193B (16% identical).
Diseases named in the same sentence as FAM193A in open-access papers:
FAM193A is named in the same sentence as 5 diseases in open-access papers, as found by Europe PMC text mining. Sharing a sentence is not in itself a finding about the gene and the disease. The quoted sentences say what the papers report.
osteoporosis (1 paper, 2019). A condition of reduced bone mass, with decreased cortical thickness and a decrease in the number and size of the trabeculae of cancellous bone (but normal chemical composition), resulting in increased fracture incidence. "In the osteoporosis group, VEGFA, DFFA, and FAM193A genes showed a significant association." (PMID 31747953, 2019). "Excluding genes without known specific functions (CDC27 and TNRC18), ARID2, HEBP1, LTBP1, and PLVAP were the only significant differences in the cancer group revealed by the gene-score methodology, while DFFA, FAM193A, and VEGFA were the only significant differences in the osteoporosis group." (PMID 31747953, 2019).
movement disorder (1 paper, 2017). Neurological conditions resulting in abnormal voluntary or involuntary movement, which may impact the speed, fluency, quality and ease of movement. "Other genes, such as GAK, HTT, TMEM175, FAM193A, and DGKQ, were mainly related to movement disorders (adjusted p-value = 0.0001) and basal ganglia disease (adjusted p-value = 3.73e-05)." (PMID 28118382, 2017).
FAM193A also shares sentences with these, for which no sentence is quoted: cancer (1 paper); insomnia (1); tumor (1).